TTLL13 (tubulin tyrosine ligase like 13)
Description:
Polyglutamylase which modifies tubulin, generating polyglutamate side chains of variable lengths on the gamma-carboxyl group of specific glutamate residues within the C-terminal tail of tubulin. Mediates ATP-dependent polyglutamate side-chain elongation of the polyglutamylation reaction but not the initiation step (By similarity). Preferentially modifies the alpha-tubulin tail over a beta-tail (By similarity). Mediates spindle-pole microtubule glutamylation in a CFAP100-dependent manner, a modification necessary for maintaining spindle-pole integrity and ensuring proper spindle assembly.
Synonyms: TTLL13P; FLJ46079; MGC33417
Tractability: Antibody: the Human Protein Atlas places it where antibodies can reach.
Gene: Protein-coding gene on chromosome 15 (90,249,530 to 90,265,482, forward strand). Ensembl gene ENSG00000213471.
Subcellular location: Cytoplasm, cytoskeleton, spindle pole
Subcellular location (Human Protein Atlas): Cytosol; Plasma membrane; Basal body
Pathways (Reactome):
Metabolism of proteins: Carboxyterminal post-translational modifications of tubulin
Gene Ontology:
Molecular function: protein binding; tubulin-glutamic acid ligase activity; protein-glutamic acid ligase activity, elongating; tubulin binding
Biological process: microtubule bundle formation; protein polyglutamylation
Cellular component: spindle pole; ciliary basal body; cytosol
Genetic constraint (gnomAD): Loss-of-function variants: 79 observed, 87.5 expected, observed/expected ratio (o/e) 0.9, 90% interval 0.75 to 1.09. The upper end of that interval is the gene's LOEUF score, 1.09, which puts it in group 4 of 6, group 1 being the genes least tolerant of losing a copy. Missense variants: 884 observed, 972.7 expected, observed/expected ratio (o/e) 0.91, 90% interval 0.86 to 0.96. Synonymous variants: 313 observed, 358.35 expected, observed/expected ratio (o/e) 0.87, 90% interval 0.8 to 0.96.
Homologues: Orthologues: chimpanzee TTLL13 (99% identical), macaque TTLL13 (96% identical), dog TTLL13 (83% identical), rat Ttll13 (82% identical), rabbit TTLL13 (79% identical), pig TTLL13 (77% identical), guinea pig TTLL13 (76% identical), mouse Ttll13 (75% identical), tropical clawed frog ttll13 (54% identical), Drosophila melanogaster TTLL6A (32% identical). Paralogues in human: TTLL6 (44% identical), TTLL7 (29% identical), TTLL11 (22% identical), TTLL4 (21% identical), TTLL2 (18% identical), TTLL1 (16% identical), TTLL9 (15% identical), TTLL3 (14% identical), TTLL10 (14% identical), TTLL8 (12% identical), TTLL12 (12% identical), KPRP (8% identical).
Diseases named in the same sentence as TTLL13 in open-access papers:
TTLL13 is named in the same sentence as 4 diseases in open-access papers, as found by Europe PMC text mining. Sharing a sentence is not in itself a finding about the gene and the disease. The quoted sentences say what the papers report.
bacterial infection (1 paper, 2017). "Consistently, Ttll4−/− and Ttll13−/− mice succumbed to bacterial infection." (PMID 28794449, 2017).
cancer (1 paper, 2022). A tumor composed of atypical neoplastic, often pleomorphic cells that invade other tissues. "However, as TTLL13 basal expression levels are either low or undetectable in normal tissues, its overexpression in human cancer results in TTLL13 expression levels that are well below those of downregulated TTLL11." (PMID 36414642, 2022).
infection (1 paper, 2017). The state of being infected such as from the introduction of a foreign agent such as serum, vaccine, antigenic substance or organism. "Following infection with C. rodentium, Ttll4−/− and Ttll13−/− mice displayed much more persistent intestinal damage, encompassing greater epithelial injury, crypt hyperplasia, and more infiltration of inflammatory cells, than those of their littermate WT control mice." (PMID 28794449, 2017).
TTLL13 also shares sentences with these, for which no sentence is quoted: atopic dermatitis (1 paper).